RNU1-89P (RNA, U1 small nuclear 89, pseudogene)
Gene: Small nuclear RNA gene on chromosome 4 (135,995,929 to 135,996,092, reverse strand). Ensembl gene ENSG00000207322.
Homologues: Orthologues: chimpanzee U1 (98% identical), guinea pig U1 (85% identical). Paralogues in human: RNU1-1 (97% identical), RNU1-2 (97% identical), RNU1-27P (97% identical), RNU1-28P (97% identical), RNU1-3 (97% identical), RNU1-4 (97% identical), RNVU1-18 (97% identical), RNVU1-29 (97% identical), U1 (97% identical), RNVU1-28 (96% identical), RNVU1-7 (96% identical), RNVU1-31 (96% identical), and 134 more.